CXCL1 (C-X-C motif chemokine ligand 1)
Diseases named in the same sentence as CXCL1 in open-access papers (continued):
Sharing a sentence is not in itself a finding about the gene and the disease.
tumor (continued). "In turn, ID4 enhances post-transcriptionally the expression and secretion of pro-angiogenic cytokines IL8 and GRO1/CXCL1, stimulating tumor neo-vascularization." (PMID 30538286, 2019). "CXCL1/2 recruit CD11b(+)Gr1(+) myeloid cells into the tumor, which produce chemokines including S100A8/9 that enhance cancer cell survival, chemoresistance and metastasis." (PMID 31998654, 2019). "Single-cell transcriptional analysis of tumor cells revealed that several secreted factors involved in recruitment or chemotaxis of myeloid cells were increased, including Cxcl1, Cxcl2, Tgfβ3, and lactotransferrin (Ltf) after short-term Ab + Pal treatment." (PMID 31444334, 2019). "In the SC level, CXCL1 mRNA and protein levels are increased after nerve injury, inflammation, and tumor cell inoculation." (PMID 30606213, 2019). "Three fractions of RT increased the concentrations of seven inflammatory mediators in tumor tissues: GM-CSF, IL-17, CXCL1, CXCL2, CCL2, CCL5 and TNFα." (PMID 31752313, 2019). "CAFs overexpress pro-inflammatory chemokines and cytokines such as IL-6, COX-2, and CXCL1, which mediate tumor-related inflammation and induce carcinogenesis." (PMID 31888563, 2019). "Considering the primary biological function of this chemokine, it’s likely that overexpressed CXCL1 also recruits neutrophil to tumor microenvironment, which was proven in some other types of cancer such as breast cancer." (PMID 31500632, 2019). "In summary, this work suggested a RelA/CXCL1/CXCR2 axis as a major guardian against PDAC tumor development." (PMID 31561620, 2019). "For further confirmation, CXCL1-induced promotion of tumor cell migration was abolished by neutralizing antibodies against CXCR1/2—two classical chemokine receptors for CXCL1 or selective CXCR1/2 antagonist SCH527123." (PMID 31500632, 2019). "Pro- tumor neutrophils induce progression disease and release of CXCL1, MMP9, VEGF, and TNFα, whose reduction suppresses tumor growing." (PMID 31799175, 2019). "While this study suggests a tumor-promoting effect of CXCL1, another study describes a central role for this chemokine in oncogene-induced senescence (OIS)." (PMID 31561620, 2019). "Further analysis showed that macrophage chemoattractants MCP-1 (CCL2) and MIP-1α (CCL3) and neutrophil chemoattractants MIP-2 (CXCL2) and KC (CXCL1) were significantly elevated, and these chemokines were secreted by K-ras activated tumor cells." (PMID 32039025, 2019). "Circulating levels of IL-1β and CXCL1 were higher in the light phase for tumor-free control mice (IL-1β: t8 = 2.3, p < 0.05; CXCL1: t8 = 10.9, p < 0.0001), but these time-of-day differences were lost in both the tumor-bearing and -resected mice." (PMID 31019214, 2019). "As a primary target cell type of CXCL1, neutrophil plays an obscure role in the tumor microenvironment and have thus become a focus of research only in the last few years." (PMID 31500632, 2019). "LPS stimulation of tumor hepatocytes further enhanced the expression of inflammatory cytokines and chemokines Ccl2, Cxcl1, Cxcl2, Tnfa, and Il6." (PMID 30990169, 2019). "For example, we have previously shown that the local tumour microenvironment of mCRC patients contains high levels of the chemokines CXCL1, CXCL5, and CCL2 which have proangiogenic properties." (PMID 29535825, 2018). "Elevated CXCL1 expression in BC stroma correlates positively with tumor grade, disease recurrence, and decreased patient survival." (PMID 30034618, 2018). "MLACs directly stimulate tumor cell growth by activating the CXCL1/2/5-CXCR2 signaling axis in tumor cells." (PMID 29541408, 2018). "CXCL1 is involved in multiple cancer biological processes including angiogenesis, metastasis, tumor growth and chemoresistance." (PMID 30158589, 2018). "It is notable that MDSCs infiltrating primary tumor lesions by sensing CXCL1, CXCL2, and CXCL5 promote epithelial-mesenchymal transition (EMT) and dissemination of cancer cells, by secreting TGF-β, EGF, and HGF." (PMID 30591657, 2018).
tumor (continued). "Mice with tumors had elevated levels of inflammatory cytokines including IL-1α, IL-6, MIP-1α and G-CSF and lower levels of TNFα and CXCL1 compared to non-tumor bearing mice (all p < 0.05; statistics are provided in S1 Table)." (PMID 30532184, 2018). "Neutrophils are attracted by various ligands including CXCL1, CXCL2, CXCL5 to tumor site and play central roles as tumor-associated neutrophil (TAN) in tumor inflammation and development from initiation to metastasis." (PMID 30220913, 2018). "Elevated serum and tissue levels of IL-6 and IL-8 are markers of poor clinical outcome in breast cancer and, along with CXCL1, both IL-6 and IL-8 have been implicated in TNBC tumor progression in vivo." (PMID 30111846, 2018). "Tumor cells are reported to have elevated levels of chemokine (C-X-C motif) ligand 1 (CXCL1), a chemokine that plays a role in inflammation and tumorigenesis, as well as interleukin-6 (IL-6), a cytokine that prevents immune dendritic cell development." (PMID 29342862, 2018). "One dominant downstream effector pathway was the Cxcl1/Cxcr2 axis, as shown by inhibition of tumor growth by the Cxcr2 antagonist SB25002, and the inability of EO771/shCxcl1 cells to sustain tumor proliferation in syngeneic mice." (PMID 29632317, 2018). "The migration of tumor-isolated MDSCs from HM-1-bearing mice was augmented by CXCL1 and CXCL2 in a dose-dependent manner." (PMID 29703902, 2018). "Cxcl1 KD phenocopied the effects of Plac1 KD on tumor growth, and overexpression of Cxcl1 partially rescued Plac1 KD cells." (PMID 29632317, 2018). "Kershaw and colleagues have demonstrated that expression of CXCR2 improved T-cell migration in a melanoma tumor which produced CXCL1, a chemokine commonly secreted by tumor cells." (PMID 29872437, 2018). "It is also reported that introduction of CXCR2 in tumor antigen specific CD8+ T cells enhances their infiltration into the tumor that expresses the ligand CXCL1 and thereby reduces tumor growth in a mouse model of colon cancer." (PMID 30483271, 2018). "The activity of aldehyde dehydrogenase (ALDH), another critical CSC indicator, was enhanced in tumor spheroids cultured with CXCL1." (PMID 30115896, 2018). "In all mice, we observed an increase in CXCL-1 expression levels within 24 hr of tumor injection and this persisted for at least 6 days." (PMID 29644002, 2018). "Two other cytokine gene expressions evolved in the same way, Cxcl1 and Cxcl2, suggesting that these chemotactic factors for neutrophil recruitment are produced by TAMs and/or tumor cells in response to inflammatory stimuli." (PMID 29662647, 2018). "ELISA analysis has also shown that colon tumor-infiltrated CD11c+ DCs produce elevated levels of CXCL1 protein, compared to the DCs isolated from normal mice." (PMID 30115896, 2018). "The IL-1α pathway has been implicated in a feed-forward signaling loop that leads to the production of pro-tumorigenic factors that contribute to malignant transformation, tumor formation and production of angiogenic factors, including CXCL1 and CXCL8." (PMID 29502208, 2018). "Particularly notable in that study was the enhanced production of IL-6, IL-8 and CXCL1 in the tumor lines resistant to anti-VEGF treatment, the same cytokines that were upregulated in stromal cells upon LTβR stimulation in our study." (PMID 29983872, 2018). "We observed an increase in CXCL-1 expression in whole livers of ILID3W mice within 3 days post tumor injection." (PMID 29644002, 2018). "Results of tumor spheroid assays reveal that CXCL1 enhanced SW620 cells to form tumor spheres, in contrast with control cells." (PMID 30115896, 2018). "CXCL1 as a potential mediator and marker of the tumor invasion of BC was elevated in the urine of BC patients." (PMID 29854840, 2018). "CXCL1, a chemotaxis-stimulating factor, recruits various stromal cells into tumor surroundings to create a pre-metastatic niche to support cancer growth, angiogenesis and metastasis." (PMID 30158589, 2018).
tumor (continued). "CXCL1 is a potent proinflammatory mediator of inflammatory diseases and infection, and is widely considered to both promote and exacerbate tumor growth and progression in several cancers." (PMID 30115896, 2018). "In all three models, we observed substantially higher migration of neutrophils from tumor-bearing mice in response to the chemokine CXCL1 or the chemoattractant fMLP than neutrophils from tumor-free littermates." (PMID 30323345, 2018). "Further analysis of the tumor samples by western blot demonstrated that blockade of TIM3 attenuates the recruitment of MDSCs by reducing chemokine CXCL1 in tumor." (PMID 28102051, 2017). "In tumor cells, its activation is altered and it drives the production of pro-angiogenic cytokines, including CXCL1 and CXCL6." (PMID 28951988, 2017). "Several cytokines, such as CCL2, CCL21, VEGF and CXCL1 are present at high levels in the tumor microenvironment and known to be involved in tumor growth promotion, vascular development, and evasion of antitumor immunity." (PMID 28969039, 2017). "In summary, our results established a critical role of tumor-derived TGF-β in triggering the influx of MDSCs into the liver through facilitating the interaction between the CXCL1/2/5 and the CXCR2." (PMID 28243237, 2017). "We found human chemokine CXCL1 was significantly highly expressed in CAFs compared with that in matched NFs as well as in tumor cells." (PMID 28518141, 2017). "The presence of a variety of factors including inflammatory cytokines [TNF-α, CXCL8 (interleukin-8), and CXCL1 (GRO-α)] have been implicated in mediating both innate and acquired resistance to taxanes and/or platinating agents in tumor cell lines." (PMID 28915246, 2017). "The cross talk of CAFs and ESCC cells induced CXCL1 expression in an autocrine/paracrine signaling loop, which further enhanced tumor radioresistance." (PMID 28518141, 2017). "Further studies revealed that CAF-secreted CXCL1 conferred tumor radioresistance by activation of DNA damage repair and Mek/Erk signaling pathway." (PMID 28518141, 2017). "CXCL1 functions to entrain IRISOE TNBC tumor cells to secrete higher levels of CCL2 and VEGF (steps 3)." (PMID 29262555, 2017). "Together, our study highlighted CAF-secreted CXCL1 as an attractive target to reverse tumor radioresistance and can be used as an independent prognostic factor of ESCC patients treated with chemoradiotherapy." (PMID 28518141, 2017). "CXCR1 and CXCR2 chemokine receptors and their ligands (CXCL1/2/3/7/8) play an important role in tumor progression." (PMID 28129639, 2017). "Compared to vehicle treatment, E7046 increased the myeloid cell-derived anti-tumor cytokine TNF-α, and reduced the levels of pro-tumor CXCL1, IL-10, and IL-6." (PMID 28920002, 2017). "Other groups also report an in vivo role for CXCL1 in drug resistance that involves paracrine signaling between tumor and myeloid cells." (PMID 28915246, 2017). "CXCL1/2, which can recruit Gr1+CD11b+ myeloid cells into tumor bed, has been reported to be highly expressed in metastatic breast cancer." (PMID 29383101, 2017). "CXCL1 is a critical cytokine involved in tumor metastasis, angiogenesis and chemoresistance and a high expression of CXCL1 has been associated with a poor prognosis." (PMID 29215599, 2017). "In order to investigate CAF-secreted CXCL1 conferred radioresistance in vivo, xenograft tumor models implanted with tumor cells alone or in combination with CAFs had been established in BALB/c nude mice." (PMID 28518141, 2017). "Together suggest that IL-1β secreted by IRISOE tumor cells activates in paracrine fashion MSCs to secrete CXCL1 that also in paracrine fashion activates IRISOE tumor cells to secrete VEGF." (PMID 29262555, 2017). "So, we demonstrated that tumor-derived CXCL1 increased the number of Ly6G+ neutrophils in the peripheral blood and tumor tissues." (PMID 27446967, 2016).
tumor (continued). "In prostate cancer the chemokines CXCL1 and CXCL2 have been implicated in promoting tumour associated bone disease by upregulating osteoclastogenesis, and in turn promoting tumour cell survival." (PMID 27761371, 2016). "Level of CXCL1 protein in tumor, which was associated with AFP levels in serum and tumor differentiation, was an independent risk factor for recurrence along with AFP, BCLC classification, and TNM stages." (PMID 27542259, 2016). "Inhibition of chemokines such as growth-regulated α protein (GROα, also named CXCL1) can also increase cell proliferation in melanoma, leading to enhanced tumor growth." (PMID 27270649, 2016). "Reduction in the neutrophil chemokine, Cxcl1, corroborated the relative decrease in wound neutrophils (Day 5 post-wounding) of tumor-bearing mice." (PMID 27548621, 2016). "When gene-engineered to express CXCR2, T cells displayed enhanced trafficking towards tumor cells secreting the corresponding chemokine CXCL1." (PMID 27096098, 2016). "In this study, we demonstrated that 3LL tumor-derived chemokine CXCL1 regulated the composition of immune cells in tumor microenvironment." (PMID 27446967, 2016). "Compared with control-sh-RM1 tumours, blood vessels in CXCL1-sh-RM1 tumours were thinner and less wide open." (PMID 27241286, 2016). "Growth curves plotted from tumor volumes show that CXCL1 expression significantly promoted tumor growth." (PMID 27542259, 2016). "In contrast, the frequency of CXCR2+ cells was comparable for control-sh-RM1 and CXCL1-sh-RM1 tumours." (PMID 27241286, 2016). "In other words, (ruxolitinib + ERBB1/2/4 inhibitor) treatment initially reduces CXCL-1, IL-8, and IL-18 expression that then rebounds in the surviving tumor cells, being over-expressed cf in vitro multiplex data in." (PMID 27379204, 2016). "CXCL1 expression was associated with perioperative alpha-fetoprotein (AFP) levels in the serum (P = 0.024) and tumor differentiation (P = 0.001)." (PMID 27542259, 2016). "CXCR1+ cells were abundant in the stroma of control-sh-RM1 tumours, while in CXCL1-sh-RM1 tumours they were sparse." (PMID 27241286, 2016). "Ki67 immunofluorescence of tumours from obese mice demonstrated a higher frequency of cell proliferation in control-sh-RM1 tumours compared with CXCL1-sh-RM1 tumours." (PMID 27241286, 2016). "Because the omental tumor tissues expressed high mRNA levels of CCL20 instead of CXCL1/2, we compared chemokine network in the omental tumor tissues with that in the parental cells (SKA and SKCXCR2 cell line)." (PMID 27723802, 2016). "The results showed that 3LL negative control cells (NC) grew aggressively in vivo, while knockdown CXCL1 expression in 3LL cells (shCXCL1) significantly attenuated tumor growth." (PMID 27446967, 2016). "As expected, the frequency of CD11b+Gr1+ MDSCs, a population including neutrophils, was decreased by twofold in tumours on CXCL1 silencing in both lean and obese mice." (PMID 27241286, 2016). "Immunofluorescence analysis demonstrated the CXCL1 expression by tumour cells, which was notable higher in obese mice." (PMID 27241286, 2016). "CXCL1 also contributes to tumor cell transformation, growth and invasion; the knockdown of CXCL1 in CRC cells causes inhibition of cell viability, resulting in the prevention of tumor growth in mouse models." (PMID 27136535, 2016). "Tumor growth in the CXCL1 siRNA‐treated mice was significantly decreased compared with the mice that received the negative control siRNA, as observed by HE staining." (PMID 27682863, 2016). "A recent study reported that miR-200 inhibits angiogenesis by targeting IL-8 and CXCL1 secreted by tumor endothelial and cancer cells." (PMID 27484639, 2016). "Combined, these data indicate that ASCs are attracted by tumour-secreted CXCL1 synergistically acting through CXCR1 and CXCR2." (PMID 27241286, 2016). "Knocking down CXCL1 expression in 3LL cells significantly inhibited neutrophils infiltration, resulting in reducing tumor growth in vivo." (PMID 27446967, 2016).
tumor (continued). "Several genes were up‐regulated in tumor tissues during the progression period, including CXCL1, CXCL2, CXCL3, and IL‐1β, while CXCR1 expression was down‐regulated." (PMID 27682863, 2016). "To examine the source of serum CXCL1 in 3LL tumor-bearing mice, we first examined the expression and secretion of CXCL1 in 3LL cells and found that 3LL cells constitutively secreted and expressed high level of CXCL1." (PMID 27446967, 2016). "TNF-α, released in the tumour microenvironment, is linked with tumour progression inducing degranulation of the neutrophils, releasing VEGF and favouring angiogenesis with the production of CXCL8 and CXCL1." (PMID 26913068, 2016). "In this study, remarkable differences were observed in the levels of CXCL1 expression among tumor tissues by IHC staining." (PMID 27542259, 2016). "Perivascular cells expressing PDGFRβ, a mesenchymal marker of ASC40, 49, were significantly less abundant in CXCL1-sh-RM1 tumours compared with control-sh-RM1 tumours." (PMID 27241286, 2016). "The observed CXCL1 signalling-dependent stimulation of endothelial cell proliferation and tumour vascularization promoted by ASCs indicates angiogenesis as a key underlying mechanism." (PMID 27241286, 2016). "We confirmed that human ASCs also respond to CXCL1 from tumour cell-conditioned medium in the transwell assay." (PMID 27241286, 2016). "CXCL1 released from CRC cells induces CXCR2+ endothelial cell migration, causing increased tumor microvessel formation." (PMID 27136535, 2016). "Proliferation typically was observed in vascularized tumour areas, which were less abundant in CXCL1-sh-RM1 tumours." (PMID 27241286, 2016). "This suggests that CXCR1 and CXCR2 signaling provides the surviving re-grown tumor cells with a paracrine loop from IL-8 and CXCL-1 to maintain tumor cell survival." (PMID 27379204, 2016). "Recruitment to CXCL1-sh-RM1 tumours was also reduced by 2-fold for control ASCs and by 10-fold for CXCR1/CXCR2 knockdown ASCs." (PMID 27241286, 2016). "For example, Chemokine (C-X-C motif) ligand (CXCL1) plays a critical role in tumor metastasis and is demonstrated to be significantly associated with Snail expression." (PMID 27419373, 2016). "Anti-CXCL1 treatment in tumor-implanted mice reduced MDSC and TAM infiltration leading to tumor regression." (PMID 27551523, 2016). "It should also be noted that disruption of the CXCL1 axis blocked tumour recruitment of not only ASCs, but also MDSCs in both lean and obese mice." (PMID 27241286, 2016). "Confirming αSMA+ stromal cells being largely of ASC origin, in control tumours, the majority of αSMA+ cells were found to also express CXCR1+, while this coincidence of expression was significantly reduced in CXCL1-sh-RM1 tumours." (PMID 27241286, 2016). "Next, we used the transwell assay to confirm that CXCL1 secreted by tumours chemoattracts the immortalized ASCs." (PMID 27241286, 2016). "In this study, CXCL1 significantly activated the EMT pathway by upregulating the expression of E-cadherin, N-cadherin, and Vimentin in HCC cells and enhanced tumor cell invasion capacity, while reducing CXCL1 expression inhibited these processes." (PMID 27542259, 2016). "The results showed that the expression of CXCL1 in 3LL tumor was higher than that in TANs or LPS-stimulated TANs (~9-fold)." (PMID 27446967, 2016). "Our study reveals αSMA as a functional link between CXCL1 signalling and increased tumour vascularization on ASC recruitment." (PMID 27241286, 2016). "Previous studies have demonstrated that CXCL1 can induce endothelial cell migration and tube formation in vitro 26 and also acts as an angiogenic factor to promote tumor growth." (PMID 27300479, 2016). "We found that the expression of several chemokines changed over the course of tumor progression, including CXCL1." (PMID 27682863, 2016). "An inverse correlation between CXCL1 and miR- 200a was observed in frozen tumor tissues from 20 HCC patients by qPCR and northern blot." (PMID 27542259, 2016).